CCR2 (C-C motif chemokine receptor 2)
Diseases named in the same sentence as CCR2 in open-access papers (continued):
Sharing a sentence is not in itself a finding about the gene and the disease.
breast cancer (continued). "CCL2/CCR2 signalling has been shown to promote the activation of the CCL3 (MIP-1α)/CCR1 signalling cascade in breast cancer metastasis to the lung, leading to the retention of metastasis associated macrophages and colony growth." (PMID 36241867, 2022). "Specifically, PYK2 ablation inhibits Notch1 signaling and consequently reduces CCL2 secretion by breast cancer cells, and concurrently reduces the levels of CCR2, CXCR4, IL‐4Rα, and Stat6 activation in macrophages." (PMID 35092356, 2022). "To determine the associations between CCR2 and MET expression, we analyzed mRNA and protein levels in breast cancer." (PMID 35405500, 2022). "The second important chemoattractant is CCL2, which was secreted by mammary tumors and which recruited CCR2-expressing inflammatory monocytes to pulmonary metastatic sites of breast cancer." (PMID 35267547, 2022). "In a 4T1 syngenetic mouse model of breast cancer metastasis, IL-1β as a master cytokine promoted the recruitment of CCR2+ monocytes and differentiation to inflammatory monocytes." (PMID 35267547, 2022). "CCR2 overexpression in lowly invasive SUM225 breast cancer cells enhanced their growth and invasion in vivo." (PMID 35405500, 2022). "We had previously shown that CCR2 overexpression in SUM225 breast carcinoma cells (CCR2-H) enhanced the growth and invasion of MIND lesions." (PMID 35405500, 2022). "Though CCL2/CCR2 signaling is known to promote late-stage tumor growth and metastasis by enhancing macrophage recruitment to the primary tumor, CCL2 increases tumor cell growth, survival and migration by signaling to CCR2 overexpressing breast carcinoma cells." (PMID 35405500, 2022). "In breast cancer bone metastasis, MAMs are largely derived from Ly6C+CCR2+ monocytes and they express high levels of CD204 and IL4R." (PMID 34803925, 2021). "In a model of lung metastasis of breast cancer, CCR2+ MØs upon activation by CCL2 produce CCL3 to induce CCR1-mediated TAM retention in the lung, supporting involvement of multiple chemokines and receptors in tumor metastasis." (PMID 34804061, 2021). "Animal studies are currently in progress to investigate these possibilities in part by examining the effects of targeting CCR2 on DCIS progression in multiple breast cancer models." (PMID 33888841, 2021). "Conversely, CCR2 shRNA knockdown or ablation by CRISPR knockout in DCIS.com breast cancer cells inhibits the number of invasive lesions, limiting DCIS progression." (PMID 33888841, 2021). "We also studied the correlation between CCL16 and CCR2 using immunohistochemistry in 40 human breast cancer tissues." (PMID 33500726, 2021). "Overall, these studies demonstrate that CCR2 antagonists impair CCL2/CCR2 mediated growth and signaling of breast cancer cells in vitro." (PMID 33888841, 2021). "Stable overexpression of CCR2 in SUM225 breast cancer cells enhances progression of DCIS lesions to invasion." (PMID 33888841, 2021). "Previous studies have shown that CCR2 expression correlates with prostate cancer progression/metastasis 39 and breast cancer progression." (PMID 33500726, 2021). "The expression of CCL2 in breast cancer in conjunction with the infiltration of CCR2-expressing inflammatory macrophages is correlated with poor prognosis and metastatic human breast cancer." (PMID 34063828, 2021). "Transfer of human CCR2-expressing CD14+ monocytes into CSF-1 supplemented nude mice with inoculation of human MDA-MB-231-derived metastatic breast cancer cells also led to selective tumor recruitment of CD14+ monocytes to lung." (PMID 34804061, 2021). "To determine the feasibility of targeting CCR2 on breast cancer cell growth, we used a 3D culture approach, useful for modeling drug efficacy." (PMID 33888841, 2021). "In a mouse mammary intraductal injection (MIND) model that mimics DCIS formation in patients, the functional role of CCR2 has been explored in two human breast cancer cell lines: SUM225, a lowly invasive cell line, and the highly invasive DCIS.com." (PMID 33888841, 2021).
breast cancer (continued). "CCR2 overexpression in mammary tumor cell line SUM225 significantly enhanced survival and migration capacity." (PMID 34386431, 2021). "Overall, these studies demonstrate that increased CCL2/CCR2 signaling in breast cancer cells is a physiologically and potentially clinically relevant signature in DCIS progression." (PMID 33888841, 2021). "Previously, we demonstrated that CCL2/CCR2 chemokine signaling in breast cancer cell lines regulated growth and invasion through p42/44MAPK and SMAD3 dependent mechanisms." (PMID 33888841, 2021). "They found that ALDH1A1 and HTRA2 regulates CCR2‐mediated breast cancer cell growth and cellular invasion in a CCL2/CCR2 context‐dependent manner." (PMID 34708890, 2021). "We noted significant declines in the level of several transcripts associated with metastasis (Cd36, Egr3, and Maf) and tumorigenesis (Ccr2 and Ccr6) in many solid tumors including breast cancer." (PMID 33682324, 2021). "Meanwhile, monocytes recruited by CCR2 will increase the number of lung metastases in breast cancer." (PMID 34512623, 2021). "In parallel, CCL2 was found to be expressed at the site of metastatic breast cancer localization in the bones and breast cancer-derived CCL2 has acted through CCR2 to promote osteoclast differentiation and contributed to bone metastasis." (PMID 32582148, 2020). "The CCL2/CCR2 axis in breast cancer is known to be involved in the metastatic process via the recruitment of different myeloid cell subsets, including TAMs and the induction of angiogenesis." (PMID 32225066, 2020). "To determine the Th2 lymphocyte phenotype in the canine mammary tumors, we assessed the expression of CCR2, GATA3, and IL-4." (PMID 32225066, 2020). "We observed a significantly higher expression of both CXCR3 and CCR2 in canine mammary tumors that gave local or distant metastases." (PMID 32225066, 2020). "CCL2/CCR2 chemokine signaling was demonstrated to promote breast cancer progression by inducing angiogenesis." (PMID 33099574, 2020). "Relatively little is known concerning the functions of CCR2 on tumor cells, though one group reported that the binding of MCP-1 to CCR2 can induce the survival and migration of breast cancer cells." (PMID 33322474, 2020). "In summary, CCL2/CCR2 chemokine signaling regulates breast cancer cell growth and invasion through increased ALDH1A1 expression and suppression of HTRA2." (PMID 31208996, 2019). "To further the significance of CCR2 expression to breast cancer cell growth and invasion, we induced CCR2 expression in established 3D cultures." (PMID 31208996, 2019). "shRNA knockdown of CCR2 in DCIS.com breast cancer cells inhibited formation of invasive breast carcinomas in animal models." (PMID 31208996, 2019). "Recent studies have shown that CCL2/CCR2 chemokine signaling in carcinoma cells enhances breast cancer growth and invasion." (PMID 31208996, 2019). "Our results reveal that BLACAT1 promoted CCR2 expression on post-transcriptional levels through sponging miR-150-5p in breast cancer." (PMID 30733855, 2019). "CCL2 and CCR2 expression are chronically overexpressed in multiple cancer types including: glioblastoma, prostate, colon and breast cancer." (PMID 31208996, 2019). "The molecular mechanism experiments demonstrated that BLACAT1 down-regulation suppressed the proliferation and metastasis of human breast cancer cells by regulating miR-150-5p targeting CCR2." (PMID 30733855, 2019). "Mechanistically-wise, it was suggested that CCR2 regulates CCL2-induced breast cancer cell motility through MAPK- and Smad3-dependent mechanisms." (PMID 31350989, 2019). "To examine how HTRA2 functioned in a breast cancer cell line with high levels of endogenous CCR2, we overexpressed HTRA2 in parental DCIS.com cells." (PMID 31208996, 2019). "To determine the molecular mechanisms through which CCL2/CCR2 signaling regulates breast cancer cell growth and invasion, we examined for expression of downstream factors." (PMID 31208996, 2019).
breast cancer (continued). "In summary, this study demonstrates that CCL2/CCR2 chemokine signaling in breast cancer cells is an important regulatory mechanism for cell growth and invasion." (PMID 31208996, 2019). "Here, the relationship between BLACAT1, miR-150-5p and CCR2 expression in breast cancer was analyzed." (PMID 30733855, 2019). "In particular, highly invasive DCIS.com breast cancer cells expressed higher levels of CCR2 than lowly invasive SUM225 cells." (PMID 31208996, 2019). "The research verified the involvement of BLACAT1 in accelerating cell survival and metastasis through miR-150-5p targeting CCR2 in breast cancer cells." (PMID 30733855, 2019). "The data indicated that BLACAT1 promoted breast cancer cell proliferation and metastasis by miR-150-5p/CCR2." (PMID 30733855, 2019). "To examine how ALDH1A1 functioned in a breast cancer cell line with high levels of endogenous CCR2, we knocked down ALDH1A1 by stable shRNA expression in parental DCIS.com cells." (PMID 31208996, 2019). "BLACAT1 promotes human breast cancer tumorigenesis by targeting miR-150-5p/CCR2 axis, suggesting the novel molecular mechanism of breast cancer." (PMID 30733855, 2019). "Previous studies showed that HTRA2, a pro-apoptotic mitochondrial serine protease inversely corresponded to CCR2 expression in breast cancer." (PMID 31208996, 2019). "While the importance of CCL2/CCR2 signaling in macrophages during cancer progression is well documented, we recently showed that CCL2-mediated breast cancer progression depends on CCR2 expression in carcinoma cells." (PMID 31208996, 2019). "In previous studies, we demonstrated an important role for p42/44MAPK and SMAD3 in CCL2/CCR2 breast cancer cell motility." (PMID 31208996, 2019). "Using 3D cell culture and transwell invasion systems, we report that CCL2/CCR2 signaling regulates breast cancer cell growth and invasion in part by enhancing ALDH1A1 expression and suppressing HTRA2 expression." (PMID 31208996, 2019). "We found that ALDH1A1 and HTRA2 regulates CCR2-mediated breast cancer cell growth and cellular invasion in a CCL2/CCR2 context-dependent manner." (PMID 31208996, 2019). "Further data analysis showed that BLACAT1 was negatively related to miR-150-5p expression and positively related to CCR2 mRNA levels in breast cancer tissues." (PMID 30733855, 2019). "It would be of interest in the future to distinguish which pathways are mediated by paracrine versus autocrine CCL2/CCR2 signaling in breast cancer cells to regulate cell growth and invasion." (PMID 31208996, 2019). "Flow cytometry analysis of breast cancer cell lines demonstrated that CCR2 protein expression correlated with invasive potential." (PMID 31208996, 2019). "The present data demonstrated that lncRNA-BLACAT1 was upregulated in breast cancer, which promoted breast cancer cell proliferation and metastasis via down-regulating miR-150-5p by targeting CCR2 expression." (PMID 30733855, 2019). "In summary, these data indicate that CCR2 overexpression in established SUM225 spheroid cultures enhances breast cancer cell invasion." (PMID 31208996, 2019). "Doxorubicin treatment on MMTV-PyMT breast carcinoma, for induction of necrotic cell death, triggers the enhanced infiltration of CCR2-expressing monocytes." (PMID 31474975, 2019). "By immunostaining, CCR2 protein was found to be overexpressed in breast carcinoma tissues, and datamining analysis revealed that RNA levels correlated with decreased distant metastasis free survival." (PMID 31208996, 2019). "In previous studies of animal models, we showed that CCR2 expression positively regulated breast carcinoma growth and invasion." (PMID 31208996, 2019). "ALDH1A1 is a metabolic enzyme that functions as a pro-invasive factor and stem cell marker, and positively corresponded to CCR2 expression in breast carcinomas." (PMID 31208996, 2019).
breast cancer (continued). "CCR2 mediates the migration of Ly6Chi monocytes from the bone marrow to CCL2-secreting tumor milieu in PyMT spontaneous breast carcinoma, KCKO pancreatic carcinoma, and MC38 colorectal carcinoma." (PMID 31474975, 2019). "In this study, we are trying to draw attention to a CCL2 chemokine and its receptor CCR2, the levels of which are statistically significantly different in breast cancer patients compared to control groups." (PMID 30151375, 2018). "As reported, the CCR2 protein of monocytes can promote breast cancer metastasis through the Notch 3 pathway." (PMID 30381359, 2018). "We also examined the canonical MCP-1 receptor CCR2 in different subtypes of breast cancer cell lines, and the CCR2 expression was found to vary among those lines." (PMID 29594759, 2018). "For example, reduced monocyte accumulation by genetic deletion of host CCR2 expression enhances the effect of doxorubicin or cisplatin treatment on the relapse of mammary tumors in the PyMT mice." (PMID 30483271, 2018). "In mice, interference with the CCL2/CCR2 axis significantly reduced the growth of hepatocellular and renal cell carcinomas, and abrogated breast cancer metastasis." (PMID 29594035, 2018). "The C-C motif chemokine ligand-2 (CCL2) promotes breast cancer metastasis through engagement with its receptor CCR2 on macrophages." (PMID 29720474, 2018). "According to our knowledge, there are no studies of the diagnostic criteria (sensitivity and specificity) of CCL2 and CCR2 serum or plasma levels in breast cancer patients." (PMID 30151375, 2018). "A recent study also showed that another CCR2 antagonist (RS102896) can suppress liver metastasis of MCF-7 human breast cancer cells induced by estrogen." (PMID 30483271, 2018). "In the MMTV-PyMT mammary tumor model, a decrease in the number of TAMs in the tumor site was observed in Ccr2-null background animals, suggesting the importance of CCR2/CCL2 signaling in the recruitment of TAMs to tumor sites." (PMID 29686671, 2018). "It is also reported that classical monocytes expressing high levels of CCR2 preferentially migrate to metastatic tumors established by Met-1 mouse mammary tumor cells or those in the PyMT mice." (PMID 30483271, 2018). "The CCL2/CCR2 pair actively participates in tumor progression and metastasis: high serum levels of this chemokine correlated with poor prognosis in breast carcinoma patients." (PMID 30591657, 2018). "The aim of this study was to investigate plasma levels and applicability of CCL2, CCR2, and tumor marker CA 15-3 in breast cancer (BC) patients and in relation to the control groups: patients with benign breast tumor and healthy subjects." (PMID 30151375, 2018). "Studies in mice have implicated CCL2 of epithelial tumour cell origin, and macrophages expressing the CCL2 receptor, CCR2, as critical factors in metastasis of breast cancer to the bone and lungs." (PMID 28077158, 2017). "Firstly, the association between CCL2/CCR2 axis and the MAPK pathways has been found in cervical cancer, breast cancer, colon carcinoma and melanoma cells." (PMID 28424406, 2017). "High levels of TRAIL-R3 and CCR-2 expression in TEpCs identified patients with early breast cancer with poor outcomes." (PMID 28420351, 2017). "These new findings provide a rationale for further studies designed to target TRAIL-R3 and CCR-2 signaling pathways to facilitate the diagnosis, prevention, and treatment of breast cancer." (PMID 28420351, 2017). "Recent studies focused on breast cancer, prostate cancer, pancreatic cancer, and colorectal cancer implicated CCL2/CCR2 axis participated extensively in pathogeneses of tumorigenesis and metastasis." (PMID 26701209, 2016). "The use of CCR2−/− mice compared with wild type mice revealed that the impact ranitidine has on tumor development in the E0771 model of breast cancer is CCR2-dependent." (PMID 26863636, 2016).
breast cancer (continued). "Deletion of Ccr2 increased the proportion of circulating EPCs in wild type mice and the presence of mammary tumors nearly doubled this proportion." (PMID 27820834, 2016). "We have demonstrated that targeted disruption of Ccl2 and pharmacologic inhibition of CCR2 both delay the growth of mammary tumors and prolong survival of mice carrying the MMTV-neu transgene." (PMID 27820834, 2016). "Taken together, our data suggest a tumor-promoting role for CCL2 acting through CCR2 on the tumor microenvironment and support the targeting of this chemokine/receptor pair in breast cancer." (PMID 27820834, 2016). "It has been reported that targeting CCL2/CCR2 signaling axis remarkably reduced the motility and survival of breast cancer cells." (PMID 27409666, 2016). "Another study demonstrated that chemokine CCL2 and its receptor CCR2 are needed for human Vδ1T cell infiltration into various tumors including lung, prostate, liver, or breast cancers." (PMID 24565056, 2014). "At metastatic sites, CCR2+ inflammatory macrophages (Mφ) facilitate breast cancer cell extravasation, seeding and growth." (PMID 23372702, 2013). "Polymorphisms in the CCR2 gene that alters the macrophage recruitment have been reported to influence a number of diseases including AIDS, multiple sclerosis, breast cancer, carotid atherosclerosis and renal transplant rejection." (PMID 20537184, 2010). "Therapeutic strategies targeting TAMs in breast cancer have evolved from depletion approaches (CSF1/CSF1R blockade) to inhibition of monocyte recruitment (CCL2/CCR2 axis), functional reprogramming (CD40 agonism, PI3Kγ inhibition), and macrophage-directed checkpoint modulation (CD47-SIRPα axis)." (PMID 42122206, 2026). "Further, biochemical studies of breast cancer cell lines from various subtypes could be helpful in clarifying the mechanisms through which CCR2 and MET overexpression regulates CCL2 and HGF signaling." (PMID 40736024, 2025). "In addition, CCL2 also synergetic with HGF/MET pathway to promote the progression and metabolic reprogramming of breast cancer, and the combination of CCR2 knockout and MET inhibitor meritinib can more effectively inhibit tumor growth and stromal response." (PMID 41341593, 2025). "How might interactions between breast cancer cells with the microenvironment regulate CCL2/CCR2 and HGF/MET signaling?" (PMID 40736024, 2025). "Promising results have been obtained using CCL2 siRNA, CCR2 siRNA, CCL2-neutralizing antibodies, CCL2 inhibitors, or CCR2 antagonists to treat tumours like breast cancer, glioma, and hepatocellular cancer in laboratory animals that received cancer cell implantation." (PMID 38339377, 2024). "This overexpression increases monocyte recruitment and promotes the migration of HER2 + breast cancer cells through the CCL2/CCR2/MAPK pathway, underscoring the significant impact of TAM-derived MMP-11 on the progression and metastatic potential of breast cancer." (PMID 38713256, 2024). "This further exploration could be useful for cancers like pancreatic, bladder, and breast cancer, which have all been treated concurrently with anti-PD-1 and a CCR2 antagonist." (PMID 39307417, 2024). "CCR2 antagonists, tested in clinical trials for pancreatic cancer treatment, could be repurposed for patients with breast cancer." (PMID 38973385, 2024). "While both CCR2 inhibition and anti-PD-1 have failed as monotherapies for glioblastoma, preclinical murine models have shown that a CCR2 antagonist improves the efficacy of anti-PD-1 in cancers such as glioblastoma, bladder, and breast cancer." (PMID 39307417, 2024). "Significantly, our analysis of 620 breast cancer patients treated with anthracyclines or taxanes showed that patients with primary tumors expressing high levels of IL-6R or CCR2 are significantly less likely to respond to either chemotherapy compared with low receptor expression." (PMID 37607007, 2023).